FERD3L (Fer3 like bHLH transcription factor)
Description:
Transcription factor that binds to the E-box and functions as inhibitor of transcription. DNA binding requires dimerization with an E protein. Inhibits transcription activation by ASCL1/MASH1 by sequestering E proteins (By similarity).
Synonyms: bHLHa31; NATO3; NTWIST; N-TWIST; PTFB
Tractability: No criterion of Open Targets' tractability assessment is met for any kind of drug.
Gene: Protein-coding gene on chromosome 7 (19,144,782 to 19,145,421, reverse strand). Ensembl gene ENSG00000146618.
Subcellular location: Nucleus
Gene Ontology:
Molecular function: protein binding; sequence-specific double-stranded DNA binding; DNA-binding transcription factor activity, RNA polymerase II-specific; RNA polymerase II transcription regulatory region sequence-specific DNA binding; DNA-binding transcription repressor activity, RNA polymerase II-specific; protein dimerization activity; sequence-specific DNA binding
Biological process: developmental process; negative regulation of DNA-templated transcription; regulation of transcription by RNA polymerase II; negative regulation of transcription by RNA polymerase II
Cellular component: chromatin; nucleus
Genetic constraint (gnomAD): Loss-of-function variants: 9 observed, 11.69 expected, observed/expected ratio (o/e) 0.77, 90% interval 0.46 to 1.34. The upper end of that interval is the gene's LOEUF score, 1.34, which puts it in group 5 of 6, group 1 being the genes least tolerant of losing a copy. Missense variants: 264 observed, 229.11 expected, observed/expected ratio (o/e) 1.15, 90% interval 1.04 to 1.28. Synonymous variants: 122 observed, 99.68 expected, observed/expected ratio (o/e) 1.22, 90% interval 1.06 to 1.42.
Homologues: Orthologues: chimpanzee FERD3L (100% identical), dog FERD3L (84% identical), pig FERD3L (83% identical), mouse Ferd3l (79% identical), rat Ferd3l (77% identical), tropical clawed frog ferd3l (51% identical), Drosophila melanogaster Fer3 (41% identical), zebrafish ferd3l (35% identical), Drosophila melanogaster twi (21% identical), Caenorhabditis elegans hlh-8 (17% identical), Drosophila melanogaster CG33557 (17% identical), Drosophila melanogaster Hand (17% identical), and 2 more. Paralogues in human: PTF1A (30% identical), TWIST1 (25% identical), TWIST2 (25% identical), SCX (23% identical), HAND2 (22% identical), TCF15 (22% identical), MSC (21% identical), TCF21 (21% identical), BHLHA9 (19% identical), FIGLA (17% identical), HAND1 (17% identical), TCF23 (16% identical), and 1 more.
Diseases named in the same sentence as FERD3L in open-access papers:
FERD3L is named in the same sentence as 5 diseases in open-access papers, as found by Europe PMC text mining. Sharing a sentence is not in itself a finding about the gene and the disease. The quoted sentences say what the papers report.
neuroblastoma (1 paper, 2019). Neuroblastoma (NB) is the most common solid, extracranial childhood tumor. "Promoter CpG islands in FERD3L gene was found to be highly methylated in neuroblastoma cell lines causing gene silencing and poor prognosis." (PMID 30786922, 2019). "There is only one work in the literature that relates the FERD3L gene to cancer, specifically neuroblastoma." (PMID 30786922, 2019).
Saethre-Chotzen syndrome (1 paper, 2017). Saethre-Chotzen syndrome (SCS) is an inherited craniosynostosis syndrome characterized by unilateral or bilateral coronal synostosis, facial asymmetry, ptosis, strabismus and small ears with prominent crus, among other less common manifestations. "Amongst the other transcription factors specific to the r1-r2 stream Ferd3l has also been implicated in the craniofacial disorder Saethre-Chotzen syndrome, however, the remaining transcription factors have unknown roles in cranial NCCs." (PMID 28407732, 2017).
cancer (1 paper, 2019). A tumor composed of atypical neoplastic, often pleomorphic cells that invade other tissues. "FERD3L is a member of the TWIST genes family that is implicated in epithelial-mesenchymal transition (EMT) in cancer cells, a process also related to metastasis and may lead to chemo-resistance in TNBC." (PMID 30786922, 2019).
FERD3L also shares sentences with these, for which no sentence is quoted: breast carcinoma (1 paper); prostate carcinoma (1).